SOD2 (superoxide dismutase 2)
Diseases named in the same sentence as SOD2 in open-access papers (continued):
Sharing a sentence is not in itself a finding about the gene and the disease.
glioma (27 papers, 2006 to 2025). A benign or malignant brain and spinal cord tumor that arises from glial cells (astrocytes, oligodendrocytes, ependymal cells). "Additionally, SOD2 expression is linked to tumor aggressiveness, making it a potential prognostic marker for gliomas." (PMID 40867576, 2025). "Compared to SOD2 16Val homozygotes, carriers with the SOD2 16Ala allele exhibited a more than 1.86-fold increased risk of glioma occurrence (adjusted OR = 1.86; 95% CI = 1.35-2.55), where the risk increased significantly with the increasing number of variant alleles (P-trend < 0.001)." (PMID 23259684, 2012). "In gliomas, SOD2 is often overexpressed, enabling tumor cells to evade ROS-induced apoptosis and promoting their survival." (PMID 40867576, 2025). "To analyze potential prognostic effects of SOD1/2 in GB patients, we analyzed publicly available databases for SOD1 and SOD2 expression in gliomas." (PMID 39187509, 2024). "The aim of present study was to elucidate the role of expression deregulations of mitochondrial sirtuin genes and co-expression with their associated proteins (SOD1, SOD2, OGG1-2α, PARP1, GDH and HIF1α) in glioma." (PMID 36809279, 2023). "In essence, mitochondrial oxidative stress resulting from SOD2 depletion can facilitate ferroptosis and increase the sensitivity of glioma cells to erastin or TMZ." (PMID 37175412, 2023). "Results analysis showed significant down-regulation of SIRT4 (p = 0.0337), SIRT5 (p<0.0001), GDH (p = 0.0305), OGG1-2α (p = 0.0001), SOD1 (p<0.0001) and SOD2 (p<0.0001) in glioma patients compared to controls." (PMID 36809279, 2023). "It has been reported that the SOD2 increased in glioma tissues in comparison to the control tissues." (PMID 35638044, 2022). "Nevertheless, the expression levels of detoxifying enzymes such as Sod1 and Sod2 were reduced in both glioma cell lines." (PMID 34832864, 2021). "We observed that the levels of peptides for ANXA1 and SOD2 were upregulated in glioma tissues in comparison to peritumoral control tissues." (PMID 34055594, 2021). "We have also validated tumor markers such as CLU and CST3 for Meningioma, ANXA1 and SOD2 in Glioma and MAP2 for Medulloblastoma." (PMID 34055594, 2021). "SOD2 inhibitor treatment was effective to lower cell proliferation in glioma xenograft mouse models." (PMID 34319007, 2021). "Many studies have reported the role of ANXA1 and SOD2 in gliomas, by virtue of their increased expression levels in the tumor tissues." (PMID 34055594, 2021). "Single nucleotide polymorphisms in SOD2, SOD3, GPX1, and NOS1 were found to significantly increase the risk of glioma development in a Chinese population." (PMID 28108734, 2017). "Four SNPs (SOD2 V16A, SOD3 T58A, GPX1 -46 C/T, and NOS1 3’-UTR) demonstrated a significant association with glioma risk, as determined by the dominant model (variant-containing genotypes versus common homozygote)." (PMID 23259684, 2012). "Using single-locus analysis, we identified four SNPs (SOD2 V16A, SOD3 T58A, GPX1 -46 C/T, and NOS1 3’-UTR) that were significantly associated with the risk of glioma development." (PMID 23259684, 2012). "In addition, radiotherapy exacerbated DNA damage by increasing mitochondrial ROS levels, whereas glioma cells with high CYBB expression inhibited ROS accumulation by activating the Nrf2/SOD2 pathway, thereby enhancing resistance to radiotherapy." (PMID 40452834, 2025). "The regulatory mechanism of the SP1/ZFPM2-AS1/miR-515-5p/SOD2 axis in gliomas was confirmed by a study, suggesting that ZFPM2-AS1 targeting could be a useful treatment strategy." (PMID 40867576, 2025). "Many studies have reported the role of SOD2 in brain tumour, such as gliomas." (PMID 35638044, 2022). "Thus, the current study is designed to investigate expression level of SIRT3, SIRT4, SIRT5 and associated genes SOD1, SOD2, OGG1-2α, PARP1, GDH and HIF1α in glioma patients and to find out whether this expressional deregulation effects the risk of glioma." (PMID 36809279, 2023).
glioma (continued). "SOD isoforms, especially SOD2 and SOD1, have been shown in prior studies to have dual functions in glioma and glioblastoma by shielding tumor cells from oxidative stress and enhancing resistance to treatment." (PMID 40867576, 2025). "Moreover, glioma cells that stably overexpress SOD and CAT exhibit high resistance to TMZ, enhanced tumorsphere formation, and poor prognosis, and TMZ-resistant glioma cells display increased expression of CAT, SOD2, and BMI1, a protein associated with stemness and therapy resistance." (PMID 40298811, 2025). "U251 and U87 glioma cells expressed high levels of SOD1, low levels of SOD2 and very low levels of SOD3." (PMID 35978820, 2022). "qRT-PCR results showed that these two glioma cell lines expressed higher levels of SOD1, lower levels of SOD2, and very low levels of SOD3." (PMID 35978820, 2022). "Before the testing of SOD1 inhibitor on cell survival in glioma, the expression of SOD1, SOD2 and SOD3 in U251 and U87 glioma cell lines was measured." (PMID 35978820, 2022). "For Glioma tissue samples we screened several known biomarker proteins including ANXA1, SOD2 and VIM." (PMID 34055594, 2021). "Three peptides of SOD2 (GDVTAQIALQPALK, GELLEAIK and AIWNVINWENVTER) showed a cumulative positive fold change of 2.48 in Glioma samples as compared to the peritumoral controls." (PMID 34055594, 2021). "Our previous studies also revealed increased expression of CAT, superoxide dismutase 2 (SOD2), and BMI1, a protein related to stemness and therapy resistance, in TMZ-resistant glioma cells." (PMID 34943091, 2021). "We examined 16 single nucleotide polymorphisms (SNPs) of 9 antioxidant genes (GPX1, CAT, PON1, NQO1, SOD2/MnSOD, SOD3, and NOS1*2*3) in 384 glioma and 384 control cases in a Chinese hospital-based case–control study." (PMID 23259684, 2012). "Thus, SOD isoforms, especially SOD2 and SOD1, have two functions in glioma and glioblastoma: they shield tumor cells from oxidative stress and help them become resistant to treatment." (PMID 40867576, 2025). "Similarly, another model for predicting the prognosis of lower-grade gliomas, which is based on four RNA-edited sites (PRKCSH chr19:11561032, DSEL chr18:65174489, UGGT1 chr2:128952084, and SOD2 chr6:160101723), also reported an AUC of 0.823." (PMID 39764127, 2024). "Present study was purposed to figure out the expression level of mitochondrial sirtuins (SIRT3, SIRT4, SIRT5) and related genes (GDH, OGG1-2α, SOD1, SOD2, HIF1α and PARP1) in 153 glioma tissue samples and 200 brain tissue samples from epilepsy patients (taken as controls)." (PMID 36809279, 2023).
melanoma (26 papers, 2005 to 2025). A malignant, usually aggressive tumor composed of atypical, neoplastic melanocytes. "For example, the amplification of mitochondria via the induction of SIRT3 would selectively target aggressive melanomas with the loss of mitochondrial SOD2 mitochondria and induce cell death via ROS." (PMID 34831420, 2021). "The analysis of the two cell lines demonstrated that the resistant cell line had lost expression of SOD2, which is associated with a highly aggressive phenotype in melanoma." (PMID 34831420, 2021). "Of particular note, a homozygous minor allele TT genotype in rs8031 (SOD2) was found to be associated with reduced risk of melanoma in the bivariate regression, however significance was lost in the multivariate regression analyses." (PMID 29342889, 2018). "Our results highlighted the importance of RAC1 enzyme and cellular oxidation-metabolizing efficiency controlled by SOD2 in association with ROS-mediated risk of melanoma." (PMID 29342889, 2018). "Besides, an increased expression of SOD2 suppressed the malignant phenotype of melanoma cells in vitro, and also led to the loss of the colony-forming ability." (PMID 35326089, 2022). "We suggest that these results shall be further validated with the goal of designing novel screening targets to identify highly UV-susceptible individuals, particularly in the RAC1 and SOD2 genes, in order to take the melanoma primary prevention strategy to a precision level." (PMID 29342889, 2018). "SOD2 is known to be a major superoxide detoxifying enzyme of cells, and therefore an altered function or expression of this enzyme may lead to unbalanced redox homeostasis and thus potentially increase or decrease the risk of melanoma." (PMID 29342889, 2018). "ATP6AP2 (the prorenin receptor) has emerged as a biomarker in multiple cancers, including melanoma, and SOD2 has been reported to play context-dependent roles in melanoma, with studies supporting both tumor-suppressive and pro-tumorigenic effects." (PMID 41279463, 2025). "For instance, superoxide dismutase (SOD) activity is significantly elevated in stage III melanoma, while SOD2 activity predominantly increases in stage IV melanoma." (PMID 40507159, 2025). "The role of SOD2 in melanoma is controversial, with some studies linking lower levels to metastasis." (PMID 37297001, 2023). "After the development of BRAF inhibitor resistance, melanoma cell lines exhibit elevated levels of ROS and expression of SOD2." (PMID 35326683, 2022). "Several studies proposed that SOD2 activity or expression is altered in skin cancers, although its role is still controversial in melanoma." (PMID 35326089, 2022). "Gene expression analysis of melanomas and other cancers indicated an upregulation of SOD2 expression, while a histological examination of pigmented melanoma tissue samples revealed the upregulated expression of both SOD1 and SOD2 compared to healthy skin." (PMID 35326683, 2022). "In contrast, Schadendorf showed that serum SOD2 level was elevated in melanoma patients and, since it was correlated to the disease progression, they proposed SOD2 as a tumor marker and a sensitive biomarker in serum for monitoring melanoma." (PMID 35326089, 2022). "In that same study, the knockdown of SOD2 expression in resistant melanoma cells inhibited proliferation, while the administration of the exogenous antioxidant, N-acetyl cysteine, re-sensitized resistant cells to BRAF-inhibitor treatment." (PMID 35326683, 2022). "In the present study, it was found that the addition of the studied flavones caused oxidative stress in the melanoma cells, for which there was also an increase of the SOD1, SOD2, GPX1 and CAT gene expression." (PMID 35059971, 2022). "Increased SOD2, as observed in treatment-resistant melanoma, prevents apoptosis from elevated oxidative stress." (PMID 34831420, 2021).
melanoma (continued). "In contrast with these findings, Church and collaborators demonstrated that increased SOD2 expression suppressed the malignant phenotype of human melanoma cells." (PMID 34943045, 2021). "We observed that dual resistant (TDR) melanoma cell lines have higher antioxidant levels (SOD2 and PRDX1), accompanied with higher ROS levels compared to counterpart parental and dabrafenib resistant (DR) cells." (PMID 32585852, 2020). "Our study suggests that SOD2 is induced in BRAF mutant melanomas rendered resistant to dabrafenib and trametinib treatment." (PMID 32585852, 2020). "Our data indicate that both NF-κB and SOD2 are upregulated in response to BRAF pathway inhibitor resistance in melanoma cells, which correlated to high oxidative stress." (PMID 32585852, 2020). "The involvement of SOD2 in mediating an effect on proliferation in TDR cells was confirmed by siRNA mediated silencing, where knockdown of SOD2 significantly suppressed melanoma cell proliferation and growth." (PMID 32585852, 2020). "In contrast, minor alleles in SOD2 rs8031 (OR 0.16, 95% CI: 0.06 to 0.39; p < 0.001) and SOD3 rs2536512 (OR 0.08, 95% CI: 0.01 to 0.31; p = 0.001) were associated with reduced risk of melanoma." (PMID 29342889, 2018). "To conclude, our initial analyses revealed an increased risk of melanoma associated with rs10951982 (RAC1), and a decreased risk associated with rs8031 (SOD2)." (PMID 29342889, 2018). "Depletion of SOD2 enhanced the ability of 6-thio-dG to induce apoptosis of NRAS-mutant melanoma cells." (PMID 29695835, 2018). "High SOD2 expression can suppress melanoma’s malignant phenotype in vitro, but serum SOD2 levels may increase in melanoma patients and correlate with disease progression." (PMID 37297001, 2023). "Interestingly, mimicking SOD2 with the mitochondrial superoxide scavenger (2-(2,2,6,6-tetramethylpiperidin-1-oxyl-4-ylamino)-2-oxoethyl) triphenylphosphonium chloride induced melanoma-cell line death and apoptosis and reduced tumor size in mouse xenografts." (PMID 35326683, 2022). "For instance, BRAF inhibitor-resistant melanoma cells are observed to have elevated reactive oxygen species (ROS) and correspondingly display higher levels of the reactive oxygen detoxification enzyme SOD2." (PMID 34831420, 2021). "Furthermore, these dabrafenib-resistant melanoma cells had upregulation of the mitochondrial enzyme, manganese superoxide dismutase 2 (SOD2), which functions to reduce ROS levels in the mitochondria." (PMID 32585852, 2020). "Our results highlighted the importance of RAC1, SOD2, and SOD3 variants in the risk of melanoma." (PMID 29342889, 2018). "As ROS signaling can induce the expression of FOXO transcription factors, FOXO along with the transcriptional co-activator PGC-1α could enhance the expression of detoxifying enzymes genes such as SOD2 in NRAS-mutant melanoma cells." (PMID 29695835, 2018). "For example, it has been demonstrated that increased SIRT3 expression is found in cancer such as oral squamous cell carcinoma and melanoma, suggesting that this could lead to concomitant increases in SOD2 activity." (PMID 29099803, 2017). "Moreover, these double-resistant melanoma cells showed an increase in SOD2 levels." (PMID 34943045, 2021). "From our data analysis, 14% of the melanoma patients showed alteration on the SOD1 gene, 7% on SOD2, and 4% on SOD3." (PMID 35326089, 2022). "By integration of RNA‐seq and RPPA analysis, we found that PAR, IGFBP2, Connexin 43, and SOD2 were similarly altered in both assays, emphasizing their significance in the regulatory role of ALDOC of melanoma malignancy." (PMID 33274599, 2021). "As a key regulator of SOD2, we observed a significant upregulation in NF-κB in TDR cell lines versus parental drug sensitive melanoma cells." (PMID 32585852, 2020).
melanoma (continued). "Herein, we found that SOD2 levels are upregulated in trametinib- and dabrafenib- resistant (TDR) melanoma cell lines." (PMID 32585852, 2020). "Five SNPs, namely rs1049255 (CYBA), rs4673 (CYBA), rs10951982 (RAC1), rs8031 (SOD2), and rs2536512 (SOD3), exhibited significant genotypic frequency differences between melanoma cases and healthy controls." (PMID 29342889, 2018). "Further, the level of radioprotection gene SOD2 and tumor suppressor PTEN were downregulated in melanoma cells while upregulated the expression levels in HEM, suggesting that the DNA damage repair and radioprotection of normal skin cells are actively enhancing the survival of normal cells." (PMID 36241419, 2023). "We observed a decrease in cell growth for both TDR cell lines versus the control after SOD2 knockdown, suggesting that SOD2 could be a factor in modulating tumor proliferation and survival in trametinib- and dabrafenib-resistant (TDR) melanoma cell lines." (PMID 32585852, 2020). "Based on our previous findings that antioxidants, such as SOD2 and peroxiredoxin-1 (PRDX1), are elevated in dabrafenib resistant (DR) melanoma cells identified from a proteomics screen, we aimed to assess SOD2 and PRDX1 levels in BRAF and MEK inhibitor-resistant cells." (PMID 32585852, 2020). "After adjusting for these risk factors, rs1049255 (CYBA), rs4673 (CYBA), rs8031 (SOD2), and rs2536512 (SOD3) were no longer associated with melanoma risk in all three models (p > 0.00238)." (PMID 29342889, 2018).
bladder cancer (25 papers, 2014 to 2025). "A single mutation in WTAP was found to increase the expression of SOD2 which was linked to the healthy status of other tissues adjacent to bladder cancer in humans." (PMID 39596561, 2024). "SNP rs5746136 of superoxide dismutase 2 in m6A modulators was strongly associated with the risk of bladder cancer." (PMID 35220962, 2022). "For bladder cancer, SOD2 expression was negatively associated with methylation levels at two CpG sites (cg06346099 and cg10698098, P < 0.05)." (PMID 31929112, 2020). "Recent studies have shown that SOD2 is consistently increased in high-grade and advanced-stage bladder cancer and is implicated in promoting cancer cell migration in tongue squamous cells." (PMID 25402510, 2015). "Similarly, carriers of SOD2 Ala16Val exhibited a higher risk of bladder cancer, particularly among concurrent smokers." (PMID 26881045, 2016). "Oxidative stress has been reported to play the pivotal factor for inducing cancer development and metastasis, and SOD2, a critical component in regulation of reactive oxygen species, is also thought to be closely associated with bladder cancer invasion and metastasis." (PMID 25402510, 2015). "Taken together, our study unravels an inverse relationship between cell migration and invasion in human bladder cancer T24T cells and suggests a novel mechanism underlying the divergent roles of SOD2 and MMP-2 in regulating metastatic behaviors of human bladder T24T in cell migration and invasion." (PMID 25402510, 2015). "Thus, the A allele of rs5746136 in SOD2 was associated with a reduced risk of bladder cancer." (PMID 36291923, 2022). "The underlying pathology includes increased RONS, MDA, NO, 8‐iso‐PGF2α, and decreased SOD2 levels in bladder cancer progression." (PMID 40755497, 2025). "It is noteworthy to mention that when polymorphisms of both GPX1 and SOD2 genes were analyzed in combination, the presence of GPX1 Pro allele increased the OR for bladder carcinoma risk (1.55 to 2.16 times)." (PMID 36676755, 2023). "The overexpression of SOD2 inhibited the proliferation, migration and invasion of bladder cancer cells, which suggested that SOD2 acted as a tumor suppressor gene for bladder cancer." (PMID 36291923, 2022). "In silico tools showed evidence that the expression of SOD2 is downregulated in both prostate and bladder cancer tissues as compared to that in control." (PMID 31929112, 2020). "Results from in silico tools indicated that the expression of SOD2 was downregulated in both prostate and bladder cancer tissues as compared to the control samples." (PMID 31929112, 2020). "Results from in silico tools showed that the expression of SOD2 is downregulated in both prostate and bladder cancer tissues." (PMID 31929112, 2020). "All results indicate that SOD2 has an inhibitory effect on JNK/AP-1 activation in bladder cancer T24Tcells." (PMID 25402510, 2015). "We demonstrated that SOD2 was a critical factor in regulating bladder cancer cell migration in T24/T24T cells." (PMID 25402510, 2015). "Recent studies have shown that SOD2 is consistently increased in high-grade and advanced-stage bladder cancer and plays an important role in cancer development and cancer metastasis." (PMID 25402510, 2015). "rs5746136 regulated the expression levels of SOD2 by guiding the binding of hnRNPC to SOD2, which acted as a critical tumor suppressor by promoting apoptosis and inhibiting the proliferation, metastasis, and invasion of bladder cancer cells." (PMID 35220962, 2022). "Expression of SOD2 was especially decreased in Asian bladder cancer subjects (P < 0.05)." (PMID 31929112, 2020). "Nevertheless, SOD2 promoter methylation level was upregulated in bladder cancer subjects." (PMID 31929112, 2020). "SOD2 expression is downregulated in both prostate and bladder cancer, as compared to the control." (PMID 31929112, 2020).